HMGB1 (high mobility group box 1)
Diseases named in the same sentence as HMGB1 in open-access papers (continued):
Sharing a sentence is not in itself a finding about the gene and the disease.
Sepsis (continued). "Sesamin, isolated from sesame oil, reduces HMGB1 levels in sepsis synergistically with other antagonists." (PMID 40406124, 2025). "Studies have reported that calycosin can relive sepsis-induced acute lung injury (ALI) by inhibiting the HMGB1/myeloid differentiation factor 88 (MyD88)/NF-κB pathway and activating the NLRP3 inflammasome." (PMID 41463300, 2025). "Recent studies have demonstrated that circTLK1 enhances HMGB1 expression by acting as a sponge for miR-106a-5p, consequently accelerating sepsis-induced AKI pathogenesis." (PMID 40727103, 2025). "In both IRI and sepsis-induced AKI models, HMGB1 release by TECs has been implicated in the promotion of renal inflammation." (PMID 40843128, 2025). "As a central mediator in the pathogenesis of sepsis, elevated HMGB1 levels reflect increased tissue damage." (PMID 41153226, 2025). "Necroptosis disrupts cell membrane integrity during sepsis progression, enabling release of inflammatory mediators, including HSPs and HMGB1." (PMID 40817040, 2025). "There are numerous other drugs that also inhibit HMGB1 in sepsis, which still need to be verified in related muscle atrophy studies." (PMID 39963819, 2025). "Vitamin D has been found to be involved in regulating the HMGB1 pathway and plays a role in muscle atrophy‐related diseases, including sepsis." (PMID 39963819, 2025). "Once released from ferroptotic or stressed cells, HMGB1 exacerbates inflammation in sepsis, leading to inflammatory cytokine release, including IL-1β, IL-18, and tissue damage." (PMID 41250137, 2025). "During sepsis, the interaction between alarmins (e.g., HMGB1, PTX3) and multiple PRRs (e.g., TLR4, MD2, RAGE) activates caspase-11-mediated pyroptosis." (PMID 40817040, 2025). "In sepsis, HMGB1 is involved in a series of cascade reactions that induce cellular pyroptosis, promoting the inflammatory process." (PMID 39963819, 2025). "Overall, CDDO-Im alleviates NLRP3 inflammasome activation and HMGB1 release through the Nrf2 pathway, thereby activating mitophagy in sepsis-related ARDS." (PMID 40599023, 2025). "Previous studies have shown that HMGB1 antagonists effectively reduce mortality in a mouse sepsis model by blocking the HMGB1-RAGE signaling pathway." (PMID 41210848, 2025). "In-depth research on HMGB1 has shown that HMGB1 is associated with TLR-4-mediated inflammatory response and a variety of diseases, such as sepsis, gliomas, and PD." (PMID 40385486, 2025). "Most importantly, CDDO-Im alleviated sepsis-associated ARDS, as evidenced by improvements in alveolar septal thickening, interstitial edema, and HMGB1 expression in BALF." (PMID 40599023, 2025). "Elevated HMGB1 in sepsis exosomes induces pyroptotic cell death and further cytokine release in target cells." (PMID 40787977, 2025). "Given the overwhelming inflammation in response to infection in sepsis, the protein content of the inflammatory markers HMGB1 and haptoglobin was evaluated." (PMID 40371344, 2025). "Due to its dual intra- and extracellular activity, HMGB1 has been studied in relation to different types of cancers, correlating to poor prognosis, and to sepsis." (PMID 40429966, 2025). "HMGB1, a nuclear protein released from dying cells, was first identified as a key mediator of endotoxicity and sepsis (29, –, 31)." (PMID 39699172, 2025). "Elevated extracellular HMGB1 correlates with disease severity in sepsis, and importantly, blocking HMGB1 or its receptors has shown protective effects in preclinical models." (PMID 41226481, 2025). "In these conditions, HMGB1 can interact with TECs and promote active secretion of IL-1 and IL-6, which can aggravate sepsis and SA-AKI." (PMID 40429966, 2025). "In the context of sepsis pathology, HMGB1 is a delayed mediator of sepsis-induced inflammation and plays a role in amplifying neuroinflammation." (PMID 39473252, 2025).
Sepsis (continued). "Collectively, these results suggest that hepatocytic GSDMD is responsible for the release of HMGB1, ultimately resulting in systemic vascular injury and lethality in sepsis." (PMID 39927458, 2025). "The data obtained from clinical patients revealed elevated levels of multiple cytokines (such as IL-1, TNF-a, IL-8 and HMGB1) in the CSF following sepsis." (PMID 39473252, 2025). "Increased circulating HMGB1 correlates with many inflammatory diseases, that is, sepsis, viral respiratory infections, traumatic brain injury, systemic lupus erythematosus, Alzheimer’s disease, cancer, and others (42, –, 46)." (PMID 39699172, 2025). "The subgroup with elevated bile HMGB1 levels exhibited a higher incidence of complications, including 7 cases of biliary pancreatitis, 19 cases of sepsis or septic shock, and 7 cases of mortality." (PMID 40054422, 2025). "HMGB1, as a highly regarded potential therapeutic target, has demonstrated significant research value in sepsis, autoimmune diseases, and various cancers." (PMID 41296391, 2025). "CircTLK1 can sponge miR-17-5p, activate the poly(ADP-ribose) polymerase 1 (PARP1)/HMGB1 axis, and aggravate the oxidative damage of mitochondrial genome (mtDNA), resulting in mitochondrial dysfunction and cardiomyocyte apoptosis in sepsis." (PMID 40041174, 2025). "HMGB1 is a nuclear protein widely recognized as a transcription factor and growth factor, which was later identified as a key mediator of severe sepsis." (PMID 40338919, 2025). "SPR was a key instrument to measure the molecular interactions between HS and proteins related to sepsis, such as histone H3 and high mobility group box 1 (HMGB1), in these studies." (PMID 40564190, 2025). "Recent investigations have shown that the amount of lactate in the blood of patients with sepsis is proportional to the amount of HMGB1." (PMID 39925738, 2025). "Lactylated/acetylated HMGB1 is released from macrophages via exosomes, impairing endothelial barrier function and exacerbating sepsis progression." (PMID 40443721, 2025). "Recent findings suggest that during sepsis, macrophages uptake extracellular lactate via MCTs, promoting HMGB1 lactylation and acetylation through a p300/CBP‐dependent mechanism." (PMID 40443721, 2025). "The synergistic effects with Rg5 have been particularly promising, with combined Rg5/Rk1 treatment showing enhanced suppression of HMGB1-mediated inflammatory responses and improved survival outcomes in sepsis models compared to individual compounds." (PMID 41155644, 2025). "The concurrent elevation of DNA, histones, and HMGB1 levels has been shown to induce coagulation dysfunction in sepsis models." (PMID 40877572, 2025). "Huanget al. reported that HMGB1-induced NLRP3 inflammasome activation contributes to the development of acute lung injury in sepsis-induced models." (PMID 40599023, 2025). "HMGB1 is indeed a well-known late mediator of sepsis that maintains cytokine release and immune cell recruitment even after initial triggers (e.g., endotoxin) subside." (PMID 41226481, 2025). "Recently, several studies have identified HMGB1 as a target for the diagnosis and treatment of sepsis." (PMID 40054422, 2025). "Paclitaxel alleviates the sepsis-induced AKI through modulation of lnc-MALAT1–miR-370-3p–HMGB1 regulatory axis." (PMID 40727103, 2025). "Paricalcitol, a noncalcified vitamin D analogue, has been found to increase survival to sepsis and significantly reduce serum HMGB1 levels." (PMID 39963819, 2025). "High mobility group box 1 (HMGB1), a key mediator of late-stage sepsis, triggers the release of proinflammatory cytokines, leading to inflammation and systemic complications." (PMID 40430548, 2025). "Extracellular HMGB1 is involved in systemic infections like sepsis, and its levels correlate with disease severity." (PMID 41153226, 2025). "WB, immunofluorescence, HE staining, and Oil Red O staining for HMGB1 in liver tissue revealed liver injury after sepsis." (PMID 39956880, 2025).
Sepsis (continued). "During sepsis, high levels of lactate induce lactylation of HMGB1 in macrophages, stimulating the exosomal release of HMGB1, which increases endothelial permeability and induces endothelial dysfunction." (PMID 40584617, 2025). "Lipoxin A4 improves renal function in sepsis by disrupting the interaction between HMGB1 and premature senescence." (PMID 40727103, 2025). "For example, in sepsis and ischemia–reperfusion injury, the HMGB1‐RAGE interaction activates the MAPK pathway (including ERK1/2, p38, and JNK), thereby driving excessive expression of pro‐inflammatory cytokines (e.g., TNF‐α, IL‐1β)." (PMID 41354099, 2025). "In sepsis, HMGB1 levels in the bloodstream correlate with DIC scores and the sequential organ failure assessment, which are crucial for tracking sepsis severity in the ICU." (PMID 39822757, 2025). "HMGB1 (high-mobility group box 1 protein) is an alarmin expressed in response to infection and a marker of sepsis." (PMID 40367285, 2025). "This study also found that elevated levels of sTREM-1 and HMGB1 were independent risk factors for SIMD, and that these markers reflect the disordered immune microenvironment in sepsis." (PMID 41477644, 2025). "Among protein biomarkers, exosomal HMGB1 is elevated in sepsis patients and correlates with disease severity and outcomes, potentially predicting septic shock or death more effectively than total HMGB1 levels." (PMID 40787977, 2025). "Pharmacological inhibition of HMGB1 has been explored, with several drugs demonstrating efficacy in reducing inflammation and muscle degradation in sepsis models." (PMID 39963819, 2025). "We initially found that CDDO-Im significantly reduced HMGB1 protein levels in the cytoplasm of lung tissue following sepsis exposure." (PMID 40599023, 2025). "In summary, these findings suggest that sepsis compromises the integrity of the BBB through various mechanisms including HMGB1 nuclear translocation, receptor activation, and immune cell infiltration; this leads to leakage of inflammatory mediators like HMGB1." (PMID 41357214, 2025). "Research has demonstrated that LPS relies on HMGB1 to amplify inflammatory responses, leading to promising therapeutic strategies targeting HMGB1 in preclinical sepsis models." (PMID 40430548, 2025). "Activation of caspase 1 (CSP-1) by the NLRP3 inflammasome during sepsis leads to pyroptosis and massive release of high-mobility group box protein (HMGB1), which is one of the lethal mechanisms of sepsis." (PMID 41315622, 2025). "It promotes the cytoplasmic localization and exosome release of High Mobility Group Box 1 (HMGB1), exacerbating the inflammatory response and organ damage in sepsis." (PMID 40766066, 2025). "For example, in sepsis, a positive feedback loop is formed between the HMGB1—TLR4 axis and the NLRP3 inflammasome, which amplifies the pro—inflammatory response." (PMID 40877572, 2025). "HMGB1 is “ate inflammatory mediator” in sepsis, and it is the center of the pro-inflammatory cytokine response network in sepsis." (PMID 40054422, 2025). "In sepsis, various DAMPs, such as HMGB1, eCIRP, and heat shock proteins serve as signals for the inflammatory response." (PMID 40783818, 2025). "The HMGB1 pathway induces ferroptosis in sepsis‐related diseases, resulting in inflammatory responses and organ damage." (PMID 39963819, 2025). "miR-181b directly targeted HMGB1, and downregulation of HMGB1 reduced inflammatory factors and myocardial injury and inhibited cardiomyocyte apoptosis in sepsis." (PMID 40041174, 2025). "Western blotting (WB) and immunofluorescence analysis of HMGB1 in CLP mice confirmed liver injury following sepsis." (PMID 39956880, 2025). "Serum levels of IL-6, TNF-α, IL-1β, and HMGB1 were markedly elevated in sepsis groups compared to Sham (P < 0.001)." (PMID 41281995, 2025). "Among them, high mobility group box 1 (HMGB1) is released by necrotic tissues in inflammatory conditions such as sepsis (Chen and Núñez 2010)." (PMID 39838305, 2025).
Sepsis (continued). "Anthraquinones derived from Rhei Radix et Rhizoma, such as emodin and rhein, protect against lung and kidney injury in experimental sepsis models through SIRT1/HMGB1 and NF-κB pathways, respectively." (PMID 41357500, 2025). "In sepsis, HMGB1 is released as a late mediator of inflammation, exacerbating systemic inflammation and contributing to multiple organ failure." (PMID 41226481, 2025). "This increase in HMGB1 correlates with its role as a poor prognostic marker for survival in severe inflammatory diseases like sepsis." (PMID 40430548, 2025). "When cells are damaged or stimulated, HMGB1 is released from the nucleus into the extracellular space and participates in the pathological process of sepsis as a late inflammatory mediator." (PMID 41244772, 2025). "Compared with the vehicle, the GSDMD activation inhibitor obviously reduced the mortality rate and plasma HMGB1 and IL-1β concentrations in the mice with sepsis." (PMID 39927458, 2025). "HMGB1 is thought to act as a late mediator because the kinetics of its release is delayed compared with most other cytokines such as IL-6 in sepsis." (PMID 39849347, 2025). "As one of the most important DAMPs, high-mobility group box 1 (HMGB1) is mainly released by innate immune cells in sepsis." (PMID 40384873, 2025). "Beyond sepsis, HMGB1/RAGE signaling contributes to pathology in sterile inflammation and chronic diseases." (PMID 41226481, 2025). "For instance, aerobic glycolysis mediated by pyruvate kinase M2 (PKM2) has been shown to promote inflammasome activation in macrophages via EIF2AK2 phosphorylation, exacerbating the release of pro-inflammatory cytokines like IL-1β and HMGB1 in sepsis." (PMID 40755920, 2025). "By inhibiting the release of HMGB1 or blocking its pathways, the systemic inflammatory response induced by sepsis can be effectively mitigated, thereby improving patient outcomes." (PMID 39963819, 2025). "Among these inhibitors, the TLR4 inhibitor TAK—242 exhibits promise in the treatment of inflammatory diseases, including sepsis and acute lung injury, by obstructing the LPS—or HMGB1—mediated signaling pathways." (PMID 40877572, 2025). "In inflammatory diseases such as sepsis, cells undergoing necroptosis also release large amounts of HMGB1, which further participates in the inflammatory response." (PMID 39963819, 2025). "Hemeoxygenase1 (HO‐1) was found to manipulate HMGB1 translocation and curb HMGB1 release, improving survival in sepsis model mice." (PMID 39963819, 2025). "In sepsis, HMGB1 levels are significantly elevated, and its release occurs later and persists longer than other inflammatory mediators, identifying it as a ‘late’ inflammatory mediator." (PMID 39963819, 2025). "HMGB1 plays a crucial role in the development of muscle atrophy during sepsis via multiple mechanisms." (PMID 39963819, 2025). "In experimental endotoxicity and sepsis, where bacterial-derived rBox A or P57799 was used to antagonize HMGB1-mediated signaling, high concentrations, and multiple doses were required." (PMID 39699172, 2025). "In a similar manner, glutamine ameliorates sepsis-induced kidney injury in mice through inhibition of HMGB1/TLR/NF-κB-driven inflammatory responses." (PMID 40727103, 2025). "Anti-HMGB1 monoclonal antibodies have shown efficacy in preclinical models of inflammatory diseases, such as sepsis and acute liver injury, by neutralizing HMGB1 and reducing the inflammatory response." (PMID 40688353, 2025). "Our results showed that HMGB 1 was expressed in each group, but the expression in the sepsis + saline group was increased, because HMGB1 is a ubiquitous protein that can be slightly expressed in normal cells, and can be upregulated by infection." (PMID 38646480, 2024). "EGCG has been reported to rescue the effects of HMGB1-induced endotoxemia and sepsis by preventing systemic accumulation of HMGB1 and its release on macrophage surface." (PMID 39682695, 2024).
Sepsis (continued). "Pyruvate kinase M2 (PKM2) plays a vital role in glycolysis’ final rate-limiting step, while high mobility group box 1 (HMGB1) acts as a powerful cytokine in the sepsis context." (PMID 38312312, 2024). "The involvement of HMGB1 in the progression of various inflammatory and autoimmune conditions such as rheumatoid arthritis, sepsis, cardiovascular disease, and cancer has been documented." (PMID 39331598, 2024). "HMGB1 is an important late inflammatory mediator (Yang, Wang & Tracey, 2001), and it plays a key regulatory role in the inflammatory response network of sepsis." (PMID 38646480, 2024). "Clinical evidence indicates a significant increase in circulating HMGB1 levels, which is positively correlated with the severity of sepsis and mortality rate." (PMID 39234245, 2024). "Our findings indicated that the inhibition of HMGB1 restrains ferroptosis and oxidative stress, thereby alleviating sepsis‐induced ALI through the activation of Nrf2 signaling." (PMID 38837857, 2024). "The cellular uptake of HMGB1 is facilitated by the formation of TN/HGMB1 complex, which induces macrophage pyroptosis that can cause hyperinflammation and immunosuppression in sepsis." (PMID 38187250, 2024). "In sepsis-associated AKI (SA-AKI) condition, HMGB1 plays a crucial role in driving sepsis via increase in glomerular fibrin deposition, renal tubular injury, and subsequent mortality." (PMID 39682695, 2024). "Wang established a mouse model of sepsis and found that plasma HMGB1 level was increased in mice with sepsis, while the expression of CD28 on the surface of CD4+T cells was inhibited, and the expression of PD-1 was increased." (PMID 39314628, 2024). "In summary, the present study revealed that inhibiting HMGB1 effectively mitigates ferroptosis and oxidative stress in sepsis‐induced ALI by activating Nrf2 signaling." (PMID 38837857, 2024). "Animal models of systemic endotoxemia have identified HMGB-1 as a late mediator of sepsis, with mice showing increased serum HMGB-1 levels 8 h–32 h after endotoxin exposure." (PMID 39416736, 2024). "Some studies have proposed incorporating HMGB1 testing into a multimodal approach to sepsis diagnosis and management, but further validation and consensus are needed before widespread implementation." (PMID 39201697, 2024). "Our recent study demonstrated a novel role of lactate in promoting HMGB1 lactylation and acetylation within macrophages, leading to consequent release of HMGB1 via exosome secretion in polymicrobial sepsis." (PMID 39372401, 2024). "Strategies that aim to inhibit HMGB1 secretion or block its activity through antibody targeting have been shown to provide protection against sepsis‐induced ALI and enhance survival rates in septic animals." (PMID 38837857, 2024). "In polymicrobial sepsis, lactate-derived HMGB1 in macrophages has elevated lactylation levels, which accumulate in the cytoplasm via exosome secretion and result in endothelial dysfunction." (PMID 38200523, 2024). "NF-κB-mediated transcription of the HGMB1 gene ultimately reduces the mRNA level of HMGB1 and attenuates the systemic inflammatory response syndrome induced by sepsis." (PMID 39711782, 2024). "During sepsis, platelet-derived exosomes carrying high mobility group box 1 (HMGB1) exacerbate vascular injury and myocardial dysfunction by promoting the formation of neutrophil extracellular traps (NETs) via the Akt/mTOR pathway." (PMID 38644472, 2024). "During sepsis, macrophages uptake lactate via MCTs, facilitating HMGB1 lactylation through p300/CBP." (PMID 38690282, 2024). "The HMGB1 protein expression was significantly increased in the sepsis + saline group but decreased in the sepsis + remazolam group." (PMID 38646480, 2024). "Our study first demonstrated that suppressing HMGB1 can upregulate the Nrf2 pathway to alleviate sepsis‐induced ALI by inhibiting ferroptosis and inflammation." (PMID 38837857, 2024).